IL18 (interleukin 18)
Diseases named in the same sentence as IL18 in open-access papers (continued):
Sharing a sentence is not in itself a finding about the gene and the disease.
Chronic colitis (4 papers, 2017 to 2023). A chronic inflammatory disease of the large intestine (colon, cecum and rectum). "The elevation of IL-1β and IL-18 levels suggests inflammasome activation, which is believed to be involved in chronic colitis." (PMID 37513865, 2023). "Recombinant IL-18 vaccines were constructed, and the effects of the vaccines were evaluated in trinitrobenzene sulfonic acid-induced acute and chronic colitis in mice." (PMID 31428451, 2019). "Interestingly, although vaccine A induced slightly higher levels of IL-18-specific IgG than vaccine D, mice immunized with vaccine A did not have any improvement in inflammatory scores, amounts of soluble collagens and IFN-γ, TNF and IL-18 levels in colon tissue in both acute and chronic colitis." (PMID 31428451, 2019). "In addition, our study revealed a negative correlation between the levels of β-hydroxybutyrate in rats with chronic colitis and proinflammatory cytokines such as TNF-α, IL-6, IL-1β, and IL-18, with a strong tendency towards a positive correlation with IL-10 levels." (PMID 37513865, 2023).
chronic prostatitis (4 papers, 2017 to 2025). An infectious or non-infectious chronic inflammatory process that affects the prostate gland. "P2X7R-NLRP3 axis could induce prostate epithelial cell pyroptosis by converting GSDMD to GSDMD-NT, which formed cell membrane pores and permitted IL-1β and IL-18 production and leakage to promote chronic prostatitis development." (PMID 38993566, 2024). "Therefore, to elucidate the association among prostate epithelial cell pyroptosis, IL-1β, IL-17A, and IL-18 production, as well as Th17 differentiation, could be helpful in understanding the pathogenesis of chronic prostatitis and identifying therapeutic targets." (PMID 38993566, 2024).
colon adenocarcinoma (4 papers, 2007 to 2022). "The somatic mutation of eight risk PRGs (CASP4, GPX4, GSDMC, TLR3, NLRP1, PLCG1, IL18, and IRF1) hardly occurred in PAAD samples but were commonly observed in colon adenocarcinoma (COAD) and stomach adenocarcinoma (STAD) ones." (PMID 35000541, 2022). "In colon adenocarcinomas, reduced or abolished IL-18 synthesis levels have been detected, thus suggesting that IL-18 may play a tumor-suppressive role." (PMID 33507690, 2021).
colorectal tumor (4 papers, 2020 to 2024). "In all colorectal tumors, we found a correlation between high IL-18 expression and high T cell infiltration, most likely because IL-18 is one of the most important immune cell-recruiting cytokines." (PMID 33255437, 2020).
cutaneous lupus erythematosus (4 papers, 2012 to 2022). An autoimmune disorder that manifests as different lupus-specific skin disorders; it can occur with systemic lupus erythematosus, or as a singular disease. "Dysregulated type I IFN signalling was common to both diseases, but DM skin lesions could be differentiated from cutaneous lupus erythematosus by a biomarker panel of five genes including IL18 (interleukin 18)." (PMID 35693792, 2022). "Thus, it seems that IL-18 regulates the development of systemic and cutaneous lupus erythematosus via TNF-α." (PMID 26690141, 2015).
cyst (4 papers, 2016 to 2023). A sac-like closed membranous structure that may be empty or contain fluid or amorphous material. "In previous studies, ADPKD cyst nephrons were shown to have elevated transcript expression of a number of inflammasome components, including IL-1β and IL-18." (PMID 36523654, 2022). "To further evaluate inflammasome activation in the kidneys of ADPKD patients, we measured the levels of IL-1β and IL-18, which are primary products of activated Caspase-1, in the cyst fluids collected from 12 different patients." (PMID 36523654, 2022). "Since P2X7 activation co-stimulates formation of the NALP inflammasome, cystic epithelial cells may be the primary sources of the IL18 and IL1β identified in cyst fluid." (PMID 27871310, 2016). "Based on our results, we conclude that S4B6-containing IL2C seems to favor survival and expansion of IL-18-driven IFN-γ secretion, possibly driving parasites towards stage conversion and cyst formation." (PMID 32753607, 2020). "Caspase-1 cleavage activates inflammatory cytokines, including IL-18, and active IL-18 is highly expressed in the kidneys, cyst fluid, and urine of ADPKD patients and animal models, indicating that caspase-1 is active in cyst cells." (PMID 37579949, 2023).
delirium (4 papers, 2011 to 2024). A disorder characterized by confusion; inattentiveness; disorientation; illusions; hallucinations; agitation; and in some instances autonomic nervous system overactivity. "Extended with the biomarkers TNF-α, IL-6, IL-18, IL-1ra, and IL-10, the 10 best biomarkers associated with delirium (all P < 0.10) were then entered into a multivariate logistic regression analysis." (PMID 22206727, 2011). "IL-6, IL-8, IL-10, IL-18, TNF-α, and chemokines (CCL2, CCL3, CXCL1, and CXCL10) have also been reported to be elevated in ICU delirium patients and are associated with delirium severity." (PMID 39308447, 2024).
experimental autoimmune encephalomyelitis (4 papers, 2011 to 2025). An autoimmune demyelinating disease of the central nervous system that is produced experimentally in animals by the injection of homogenized brain or spinal cord in Freund's adjuvant. "For example, experimental autoimmune encephalomyelitis developed normally in IL-18−/− mice, but not in IL-18Rα−/− mice." (PMID 21494550, 2011).
Fibroadenoma (4 papers, 2022 to 2025). A benign tumor of the breast characterized by the presence of stromal and epithelial elements. "In patients with BC, IL-18 was higher than the normal values by +5.0%, while in patients with fibroadenomas, IL-18 was slightly lower than normal by −2.1%." (PMID 40429927, 2025). "In the HER2(−) group, compared to the control and fibroadenomas, the highest level was shown for cytokines TNF-α (2.65 pg/mL) and IL-18 (67.05 pg/mL)." (PMID 39456554, 2024). "In addition, in the group with fibroadenomas, the lowest level compared to HER2(+)/(−) and control groups was shown for such cytokines as IL-6 (2.78 pg/mL), IL-8 (55.73 pg/mL), and IL-18 (62.5 pg/mL)." (PMID 39456554, 2024).
fibromyalgia (4 papers, 2021 to 2023). A chronic disorder of unknown etiology characterized by pain, stiffness, and tenderness in the muscles of neck, shoulders, back, hips, arms, and legs. "The top five proteins that distinguished fibromyalgia patients from plasma controls were in serum STAMBP, SIRT2, CD40, AXIN1 and IL-7 and in CSF (CCL19, CCL23, IL-18, CX3CL1, FGF19, CXCL10, CCL11)." (PMID 36327322, 2022). "The presence of ROS in fibromyalgia activates an inflammasome called NOD-like receptor family, pyrin domain containing 3 (NLRP3), which triggers the release of inflammatory cytokines, such as IL-1β and IL-18." (PMID 34239993, 2021).
Glucose intolerance (4 papers, 2016 to 2022). Glucose intolerance (GI) can be defined as dysglycemia that comprises both prediabetes and diabetes. "Taken together, it is possible that our finding that ablation of Nlrp3 did not protect mice from glucose intolerance may be attributable to counteracting effects from the gut in a setting of standard co-housing facilities and/or reduced IL-18 signaling." (PMID 27583382, 2016).
head and neck squamous cell carcinoma (4 papers, 2013 to 2021). A squamous cell carcinoma that arises from any of the following anatomic sites: lip and oral cavity, nasal cavity, paranasal sinuses, pharynx, larynx, and salivary glands. "In human head and neck squamous cell carcinoma (HNSCC), NLRP3, ASC, CASP1, IL1B and IL18 gene expression is increased as compared to oral mucosa." (PMID 33261061, 2020).
hypercoagulability (4 papers, 2013 to 2022). "In conclusion, our results may suggest that both SH and OH may be associated with ED, which is reflected by decreased fibrinolytic activity, hypercoagulability, and increased levels of IL-6, IL-12, and IL-18 and depends not only on the cause but mainly on the degree of hyperthyroidism." (PMID 24367378, 2013).
Idiopathic thrombocytopenic purpura (4 papers, 2014 to 2024). "Idiopathic thrombocytopenic purpura—usually associated with abnormal immune activity—may involve IL‐18 in its regulatory processes." (PMID 39188114, 2024). "In idiopathic thrombocytopenic purpura, a haematological disease that in some cases heralds systemic lupus, elevated serum IL-18 and higher expression of IL-18 mRNA in peripheral blood mononuclear cells (PBMC) were detected." (PMID 29422069, 2018).
immune deficiency (4 papers, 2012 to 2021). "Plasma levels of free IL18 are also increased in dialysis patients, but Th1 lymphocyte immunodeficiency was reported owing to the deficit of IFN-gamma." (PMID 22863216, 2012).
Impaired glucose tolerance (4 papers, 2015 to 2025). An abnormal resistance to glucose, i.e., a reduction in the ability to maintain glucose levels in the blood stream within normal limits following oral or intravenous administration of glucose. "It is known that elevated glucose levels have been associated with the release of IL-18 among healthy individuals and those with impaired glucose tolerance." (PMID 25625430, 2015). "Elevated blood sugar levels lead to increased circulating levels of cytokines such as IL-6, TNF-α, and IL-18, which may contribute to impaired glucose tolerance even in healthy individuals through oxidative mechanisms." (PMID 41011276, 2025).
kidney stones (4 papers, 2016 to 2024). "It should be noted that CCL2 rs1024611 and IL18 rs360719 yielded borderline associations with nephrolithiasis-related ESRD simultaneously with a significant association with the CASR rs7652589 SNP." (PMID 27739473, 2016). "Other polymorphisms, such as in the CDH1, VEGF, IL18, IL1RA, MnSOD, ORAI1, and TAP genes, have also been reported to be associated with kidney stone recurrence." (PMID 33956883, 2021). "The aim of this study was to investigate the effects of SWL, for the treatment of kidney stones, on routine blood tests, and specific biomarkers, namely NGAL, IL-18, IL-6, IL-10 and IL-8." (PMID 32487191, 2020). "Calcium oxalate crystals, a key component in kidney stones, induce an inflammatory response by activating the NLR family pyrin domain containing 3 inflammasome (NLRP3), resulting in the release of pro-inflammatory cytokines IL-1β and IL-18." (PMID 38281018, 2024).
left ventricular hypertrophy (4 papers, 2016 to 2024). Enlargement of the LEFT VENTRICLE of the heart. "Notably, the serum IL-18 levels were highly paralleled with the progression of left ventricular hypertrophy in Fabry patients receiving ERT." (PMID 27888626, 2016). "First, we examined the circulatory IL-18 levels in 25 Fabry patients who carried IVS4+919 G>A mutation and have not developed left ventricular hypertrophy (LVH)." (PMID 27888626, 2016).
leprosy (4 papers, 2019 to 2022). Leprosy is a chronic infectious disease affecting primarily the skin and peripheral nervous system. "Our results strongly argue against this possibility since loss of function mutations in IL18R1 are depleted in leprosy cases supporting the conclusion from the eQTL finding that reduced IL18 signalling is protective for leprosy." (PMID 34879060, 2021). "However, rs2058660 is an eQTL for IL18RAP in neutrophils where the allele associated with leprosy risk (and CD protection) drives lower expression of IL18RAP, hence a more subdued pro-inflammatory signalling by IL18." (PMID 34879060, 2021). "At this stage of pathogenesis, blunted IL18 signalling in leprosy either by reduced IL18RAP expression or reduced IL18 binding by IL18R1 would hinder the development of anti-inflammatory host responses, which is expected to be beneficial for countering an infectious agent." (PMID 34879060, 2021). "We also observed poor expression ofcaspase-1, IL-1β, and IL-18 in all leprosy spectrum groups." (PMID 32130367, 2020). "Since IL18 can be produced by variety of cells, including non-immune cells, this suggests that IL18 production is triggered at early stages of leprosy and CD before the onset of acquired immunity and the initiation of the IL12-IFNγ loop." (PMID 34879060, 2021).
lipodystrophy (4 papers, 2015 to 2026). A congenital or acquired disorder characterized by abnormal loss or redistribution of the adipose tissue in the body. "Recently was found that IL-18 mRNA expression was lower in skeletal muscle in patients with HIV-lipodystrophy and that IL-18 was implicated in lipid metabolism." (PMID 30477112, 2018). "Patients with HIV-infection and lipodystrophy (LD) are characterized by lipid and glucose disturbances and increased levels of circulating IL-18." (PMID 29342149, 2018). "In this study, we included material from a cohort of HIV patients with lipodystrophy in order to obtain more information about the metabolic role of IL-18 in humans." (PMID 29342149, 2018). "Patients with HIV-infection and lipodystrophy are characterized by lipid and glucose disturbances and increased levels of circulating IL-18." (PMID 30477112, 2018). "As previously demonstrated, plasma IL-18 was increased in patients with HIV-lipodystrophy compared to healthy controls (247 pg/ml vs 199 pg/ml, p<0.05)." (PMID 29342149, 2018). "Patients with HIV-lipodystrophy share some of the same metabolic disturbances as mice lacking IL-18 signalling but paradoxically the systemic levels of IL-18 are increased in those patients." (PMID 29342149, 2018). "In contrast to those studies, we found a reduced expression of IL-18 and IL-18 Receptor mRNA in skeletal muscles in patients with HIV-lipodystrophy compared to healthy controls, although circulating IL-18 was increased in those patients." (PMID 29342149, 2018). "When patients with HIV-lipodystrophy and healthy subjects were analysed individually, the same correlation between IL-18 mRNA and triglycerides remained (HIV-LD Rp = -0.51, p = 0.02; Healthy subjects Rp = -0.69, p = 0.014)." (PMID 29342149, 2018). "Indeed, IL‐18 seems to be related to fat mobilization since patients with lipodystrophy treated with acipimox and insulin have reduced plasma concentrations of IL‐18." (PMID 41508774, 2026). "In patients with HIV-lipodystrophy, low expression of IL-18 mRNA in skeletal muscle correlated to high levels of ceramides (Rp = -0.56; p = 0.038) and high levels of sphingosine-1P (IL-18 mRNA Rp = -0.54, p = 0.046)." (PMID 29342149, 2018). "The reduced IL-18 and IL-18 receptor in skeletal muscle in patients with HIV-Lipodystrophy may also be link to IL-18 resistance." (PMID 29342149, 2018). "The major finding of this study is that the expression of IL-18 mRNA and IL-18 receptor mRNA is reduced in skeletal muscle in patients with HIV-lipodystrophy compared to healthy age-matched men." (PMID 29342149, 2018). "Elevated circulating levels of IL-18 are observed in HIV-infected patients and especially those with lipodystrophy." (PMID 29342149, 2018). "We found an inverse correlation between IL-18 expression in skeletal muscle and systemic triglycerides and HDL-cholesterol in both healthy subjects and in patients with HIV-lipodystrophy." (PMID 29342149, 2018). "IL-18 mRNA and IL-18 receptor mRNA expression were reduced by 60% and 54%, respectively, in skeletal muscle in patients with HIV-lipodystrophy compared to healthy controls." (PMID 29342149, 2018). "If these two subjects were excluded, IL-18 mRNA expression was still significantly lower in patients with HIV-lipodystrophy compared to healthy controls (p = 0.003) (data not shown)." (PMID 29342149, 2018). "We hypothesized that skeletal muscle IL-18 and IL-18 receptor (R) expression would be altered in patients with HIV-lipodystrophy." (PMID 29342149, 2018). "Furthermore, low expression of muscle IL-18 mRNA correlates to high levels of ceramides in skeletal muscle and to increased levels of circulating triglycerides and low levels of HDL-cholesterol in patients with HIV-lipodystrophy." (PMID 29342149, 2018). "However, in the current study IL-18 expression was decreased and not increased in skeletal muscle in HIV-lipodystrophy, and ceramide can therefore not explain reduced expression of IL-18." (PMID 29342149, 2018).
lipodystrophy (continued). "Therefore, we conclude that IL-18 signaling pathway is impaired in skeletal muscle in patients with HIV-lipodystrophy and that the muscle cell is not a source of circulating IL-18." (PMID 29342149, 2018). "Having found that IL-18 mRNA expression was lower in skeletal muscle in patients with HIV-lipodystrophy, we investigated whether this was associated to an increased content of IMCL, as observed in mice lacking the IL-18 signalling pathway." (PMID 29342149, 2018).
liver dysfunction (4 papers, 2013 to 2023). "IL-18 was a significant predictor of myalgia (p<0.05) and a probable predictor of liver dysfunction (p=0.096)." (PMID 34367188, 2021). "It has also been demonstrated in several studies that high levels of IL-18 in AOSD patients are a predictor of liver dysfunction." (PMID 27042373, 2016). "In this patient, serum IL18 levels correlated well with serum ferritin levels and the extent of liver dysfunction but dissociated with serum CRP and IL6 levels which had remained normal after initial high-dose corticosteroids and cyclosporine therapy." (PMID 24455384, 2013). "IL18 levels were well correlated with ferritin levels and the extent of liver dysfunction during the clinical course of this patient." (PMID 24455384, 2013). "Interleukin‐1, IL‐6, IL‐18, interferon‐gamma, and TNF‐α play a key role in the pathogenesis of AOSD, and elevated IL‐1 and IL‐18 levels are closely associated with the systemic symptoms of AOSD, such as fever, rash, and liver dysfunction." (PMID 37397575, 2023). "In the present case, the serum IL‐18 levels (67,500 pg/mL) did not help in differentiating liver dysfunction as being due to AOSD or AIH." (PMID 37397575, 2023).
liver failure (4 papers, 2013 to 2021). A liver disease characterized by the liver losing or has lost all of its function. "Regarding the main MetaCore pathway associated with liver failure, the “IL-18 signaling” pathway is related to Th1 cell activation and differentiation, oxidative burst, apoptosis, cytotoxicity, immune responses, adhesion, cell migration and proliferation." (PMID 33182673, 2020). "From the clinical study, the high serum levels of HDAC2, IL-18, IL-1β were found in liver failure patients, when compared with normal subjects." (PMID 33431796, 2021). "The serum level of HDAC2, IL-18, and IL-1β in liver failure patients was higher than healthy donors." (PMID 33431796, 2021). "A recent cohort study (TRIBE–AKI Consortium) in adults used urinary biomarkers (tubular injury markers [NGAL, IL-18, KIM-1, L-FABP], tubular function markers [FeNa] and glomerular injury markers [albumin]) to differentiate between various causes of AKI in liver failure." (PMID 29497824, 2019). "A similar case with regard to dissociation between IL18 and CRP as well as IL6 was reported in which a patient was suffered from progressive liver failure requiring liver transplantation in the relapse of AOSD." (PMID 24455384, 2013).
lupus erythematosus (4 papers, 2012 to 2024). An autoimmune, connective tissue chronic inflammatory disorder affecting the skin, joints, kidneys, lungs, heart, and the peripheral blood cells. "Patients with lupus erythematosus display transitional upregulation of the IFNα/interleukin-18 (IL-18) processing machinery (a.k.a. the inflammasome)." (PMID 24279613, 2013).